IGF2 (insulin like growth factor 2)
Diseases named in the same sentence as IGF2 in open-access papers (continued):
Sharing a sentence is not in itself a finding about the gene and the disease.
Obesity (continued). "In conclusion, we report that HFD-induced obesity is paternally transmitted and is correlated with expression of the Peg3 and Igf2 imprinted genes, and that down-regulation of Peg3 and Igf2 in adipocytes can contribute to diet-induced obesity and the symptoms associated with obesity." (PMID 24416415, 2014). "Down-regulation of Peg3 and Igf2 in adipocytes could contribute to diet-induced obesity and the symptoms associated with obesity." (PMID 24416415, 2014). "Studies also supported the assumption that IGF2 is strongly associated with obesity." (PMID 25062844, 2014). "In the current report we determined whether preconceptional obesity, in the mother or the father, is associated with methylation patterns at the IGF2 DMRs in newborns using DNA from leukocytes isolated from umbilical cord blood at birth." (PMID 23388414, 2013). "Hypomethylation at the IGF2 DMR was associated with paternal obesity." (PMID 23388414, 2013). "Consequently, we found that paternal obesity is associated with a decrease in DNA methylation at the IGF2 DMR." (PMID 23388414, 2013). "Obesity is associated with elevated IGF2 circulating levels and increased estrogen levels." (PMID 23388414, 2013). "IGF2 may also regulate fat metabolism as low circulating IGF2 concentrations are associated with weight gain and obesity, whereas high circulating IGF2 levels are associated with low body weight in middle aged men." (PMID 19835573, 2009). "In addition to H19/Igf2 imprinting patterns, other genes that predispose for obesity can be affected by maternal diet." (PMID 17805414, 2007). "Furthermore, alterations in fetal growth related to H19/Igf2 imprinting are associated with metabolic disorders in adulthood, including obesity and diabetes." (PMID 17805414, 2007). "It is possible that the combination of the AMPKγ3 mutation and the wild type IGF2 gene, which confers increased fat accumulation in pigs, provides a genetic foundation upon which the addition of a hypercaloric, high fat diet causes obesity and reproductive dysfunction in the Ossabaw pig." (PMID 26046837, 2015). "In addition to fat gain, Peg3 and Igf2 might also contribute to the symptoms associated with obesity." (PMID 24416415, 2014). "However, evidence for its role as a link between early conditions and later adult disease risk comes from several other studies reporting associations between methylation shifts at IGF2 differentially methylated regions (DMRs) and increased susceptibility to e.g. malignancies, as well as obesity." (PMID 23840686, 2013). "Previous studies have reported an association between circulating IGF2 protein concentrations and high birth weight as well as risk of obesity and several cancers in adulthood, suggesting early exposures may contribute to the variation in birth weight via epigenetic alterations." (PMID 22392079, 2012). "In humans, in vitro fertilization confers a higher risk of obesity later in life, possibly due to low methylation (hypomethylation) in culture conditions of typically methylated and therefore silenced maternal alleles such as the insulin-like growth factor II (IGF-2)." (PMID 21276254, 2011). "Another study in rats demonstrated that during fetal development, the expression of Igf2 is regulated by maternal nutrient intake, potentially leading to disease phenotypes such as obesity." (PMID 39424650, 2025). "During fetal development, the expression of IGF2 is regulated by maternal nutrient intake, potentially resulting in disease phenotypes, including obesity." (PMID 39424650, 2025). "This study, in a novel way, tracks the actions and impacts of IGF-1 and IGF-2 on the human body over the course of a lifetime, considering disturbed metabolism in the course of obesity." (PMID 38612776, 2024). "Among them, IGF2/H19 is involved in the pathogenesis of obesity-related diseases such as diabetes mellitus, and evidence suggested that parental obesity impacts the DNA methylation of IGF2 in offspring." (PMID 40302954, 2024).
Obesity (continued). "Specific genes, such as insulin-like growth factor 2 (IGF2) and leptin, have shown instances of hypermethylation risk factors for CAD, like obesity." (PMID 37893238, 2023). "The cause of obesity and metabolic syndrome can be attributed to the methylation process affecting known as insulin-like growth factor 2 (IGF2) gene and the hypermethylation of two obesity-associated genes, leptin and tumor necrosis factor (TNF)." (PMID 38248733, 2023). "We report, for the first time, that DHA supplementation during pregnancy in women with obesity normalizes the increased IGF2R levels in male placentas, reducing the risk of adverse outcomes related to the IGF2/IGF2R system in male newborns." (PMID 37408866, 2023). "Several studies have found that paternal fast food intake and obesity can lead to changes in DNA methylation and expression of Meg3 and Nnat in sperm, and Igf2/H19 in the offspring." (PMID 36386900, 2022). "Collectively, our findings are strongly in favor of adding IGF2 in culture medium to overcome obesity-related meiotic structural-developmental defects by helping ameliorate the known sub-optimal culturing conditions that are currently standard with ART." (PMID 35836183, 2022). "Increased levels of IGF-2 (insulin-like growth factor 2) methylation are correlated with obesity and insulin resistance." (PMID 35326592, 2022). "The ApaI polymorphism of insulin-like growth factor 2 (IGF2) had been reported to be associated with body mass index, fat mass, grip strength and obesity in adult population." (PMID 35626807, 2022). "Low levels of circulating IGF-2 (IGF-2 < 400 ng/mL) are associated with an increased risk of weight gain and obesity." (PMID 35626807, 2022). "A comparison of the obesity and control groups revealed differences in the expression of IGF2, IGFBP1, and IGFBP7 genes." (PMID 34371941, 2021). "The use of IGF-2 as biomarkers of obesity or therapeutic targets was the subject of preliminary research." (PMID 34959885, 2021). "They found a significant decrease in methylation at the differentially methylated regions (DMRs) of the IGF2 gene among newborns of obese fathers and identified an inverse relationship between DNA methylation in offspring and paternal obesity." (PMID 33382823, 2020). "Among them, insulin-like growth factor 2 (IGF2), which is produced by one of the best known epigenetically imprinted genes, is associated with higher body weight and obesity." (PMID 31443282, 2019). "Other studies underlined the relationship between IGF2/H19 IC1 DNA methylation and the development of overweight/obesity." (PMID 30619799, 2018). "Current data about IGF2 and obesity is both limited and conflicting, so the potential role of central IGF2 in regulating energy and glucose homeostasis also need to be further elucidated." (PMID 29259155, 2017). "We previously demonstrated a negative correlation between paternal transmission of HFD-induced obesity and expression of two imprinted genes, Igf2 and Peg3 (paternal expressed gene, PEG)." (PMID 26868178, 2016). "The aim of the present study was todetermine the possible association of five single-nucleotide polymorphisms (SNPs)located in the IGF2, LEPR, POMC,PPARG, and PPARGC1genes with obesity orobesity-related risk phenotypes." (PMID 25923461, 2015). "Other studies have shown that genetic variations in several known imprinted genes, such as IGF2, INS and GNAS, have been associated with CMR traits, including adult obesity (BMI) and T2D." (PMID 26451733, 2015). "This study reports evidence for a paternal transmission of HFD-induced obesity and a correlated expression of Igf2 and Peg3 (paternal expressed gene 3) imprinted genes." (PMID 24416415, 2014). "In this study, we report evidence for paternal transmission of HFD-induced obesity, which correlated with the expression of Peg3 and Igf2 imprinted genes." (PMID 24416415, 2014). "It is evident that obesity is associated with T2DM, and IGF2 levels in T2DM patients are associated with T2DM." (PMID 25062844, 2014).
Obesity (continued). "Our data suggest an increase in DNA methylation at the IGF2 and H19 DMRs among newborns from obese mothers, but a larger study is warranted to further explore the potential effects of maternal obesity or lifestyle on the offspring's epigenome." (PMID 23388414, 2013). "Nevertheless, the data concerning associations between IGF2 DMR methylation and parental BMI or obesity reached sufficient power, especially when studying offspring from fathers with high BMI." (PMID 23388414, 2013). "Offspring exposed to maternal starvation early in gestation during the Dutch Famine in the 1940s had decreased methylation at the IGF2 DMR, an imprinted region of differential methylation within the IGF2 gene which was accompanied by obesity later in life." (PMID 23148549, 2012). "In this study we tested the possible association between two polymorphisms from the insulin – IGF2 region and T1DM, T2DM and obesity." (PMID 21637566, 2010). "We conducted a case-control study to investigate the relationship between the insulin -23Hph and IGF2 Apa polymorphisms and three common pathological phenotypes: T1DM, T2DM and obesity." (PMID 21637566, 2010). "The insulin -23Hph and IGF2 Apa polymorphisms were genotyped in Romanian patients with T1DM (n = 204), T2DM (n = 215) or obesity (n = 200) and normoponderal healthy subjects (n = 750)." (PMID 21637566, 2010). "This is the first study to simultaneously assess the relationship between insulin – IGF2 polymorphisms and T1DM, T2DM and obesity in the Romanian population." (PMID 21637566, 2010). "For example, obesity has been shown to alter germline DNA methylation profiles in mice, affect fetal and placental gene expression, and modulate offspring hepatic gluconeogenesis via IGF2/H19 gene methylation changes." (PMID 40960588, 2025). "Abnormal DNA methylations of key metabolic-related genes, such as Leptin, adiponectin, PGC1α, IGF-2, appetite-related genes-(POMC, NPY), are frequently implicated in the development of obesity and insulin resistance." (PMID 40702315, 2025). "This FTO-m6A-H19/IGF2 circuit may explain paradoxical GWAS findings linking FTOrs9939609-A to both leanness and obesity." (PMID 40055326, 2025). "Importantly, the function of the gene Igf2 encoding protein IGF-2 has been related to metabolic disease and obesity." (PMID 39612469, 2024). "The results of the relationship between H19DMR methylation with obesity and the expression of the H19 and IGF2 genes indicate that fat intake during the first trimester of pregnancy significantly impacts DNA methylation in the IGF2 and H19 genes in newborns." (PMID 39399112, 2024). "Collectively, our findings are strongly in favor of adding IGF2 in culture medium to overcome obesity-related meiotic structural-developmental defects by helping ameliorate the known sub-optimal culturing conditions that are currently standard with assisted reproduction technologies." (PMID 35836183, 2022). "Similarly, the methylation of the IGF2 (Insulin-Like Growth Factor 2) gene is associated with a higher ratio of Triglycerides to HDL-C and obesity." (PMID 36551003, 2022). "IGF-2, MEST, PEG3 and NNAT play significant role in prenatal and postnatal growth regulation and dysregulation of any of these genes are associated with developing obesity." (PMID 35022547, 2022). "Finally, IGF2BP2 also contributes to obesity and T2D through its regulation of IGF2, which participates in the pathogenesis of these diseases." (PMID 35163144, 2022). "Notably, altered IGF2 expression has been observed in metabolic conditions such as obesity, diabetes and polycystic ovary syndrome." (PMID 36572933, 2022). "Further, low IGF-2 levels have been documented in pre-puberal children with obesity." (PMID 33681100, 2021). "We speculate that the low level of IGFBP6 in obese patients cannot decrease the level IGF2 and that may be the factor that contributes to obesity." (PMID 34371941, 2021).
Obesity (continued). "This indicates that IGF-2 could stimulate the growth of adipose tissue more potently than that of other body parts, which further suggests its influence on the development of obesity." (PMID 34063412, 2021). "However, there is growing evidence that IGF2 regulatesfetal growth and development and as well participates in the development of numerousdiseases such as cancer, obesity, diabetes, and liver diseases." (PMID 33988719, 2021). "Interestingly, studies of the APAI polymorphism of the IGF2 gene have demonstrated that the APAI A allele is associated with higher serum IGF-II levels and less obesity." (PMID 34072372, 2021). "The overexpression of IGF-2 has been shown to increase incidence of obesity and diabetes." (PMID 31714944, 2019). "Previous studies had shown that parental obesity influence Igf2 by epigenetic changes which could alter the metabolic health of the fetus; however, how the locally intra-ovarian Igf2 is programmed by maternal and post-weaning HF intake is unknown." (PMID 28417351, 2017). "We previously demonstrated a negative correlation between paternal transmission of HFD-induced obesity and expression of two PEGs, Igf2 and Peg3, suggesting that these genes might contribute to fat accumulation, or the symptoms associated with obesity." (PMID 26868178, 2016). "Several imprinted genes are associated with body weight dysregulation, and we found that Peg3 and Igf2 might be involved in the paternal transmission of propensity to diet-induced obesity." (PMID 24416415, 2014). "In addition, several studies have reported the correlation between Igf2 genotype and obesity in humans." (PMID 24416415, 2014). "We explored the potential effect of parental obesity on IGF2/H19 DMR methylation in newborns." (PMID 23388414, 2013). "Prior studies have demonstrated the influence of prenatal maternal folic acid intake on offspring’s DNA methylation of IGF2, leptin, and retinoid X receptor-α gene, which have all been shown to be related to growth, energy metabolism, and appetite regulation that affected energy balance and obesity." (PMID 36678251, 2023). "In vivo assay showed that decreased Igf2 expression occurred with fat deposition and obesity, which may not be caused by an increase in food intake, but more likely by changes in energy homeostasis." (PMID 33746902, 2021). "Moreover, IGF-2/IR-A signaling may promote carcinogenesis, especially in conditions with increased IR-A/IR-B ratio (like obesity and type 2 diabetes)." (PMID 33673334, 2021). "Our data suggest that variation in IGF2 DMR methylation is an important mechanism by which circulating IGF2 concentrations, a putative risk factor for obesity and cancers of the colon, esophagus, and prostate, are modulated; associations that may depend on pre-pregnancy obesity." (PMID 22392079, 2012). "Children experiencing overweight or obesity tend to have higher serum levels of insulin-like growth factor 1 (IGF-1) and insulin-like growth factor 2 (IGF-2), specifically during the phase before or at the onset of puberty." (PMID 38612776, 2024). "Concentrations of IGF-2, the key PLAG1 target gene, were shown to be higher in children with obesity compared to the control group, and were found to be associated with increased leptin levels in adult, normal-weight patients." (PMID 34684585, 2021). "IGF1 and IGF2 are highly expressed in CRC, and a variety of metabolic disorders such as obesity, dyslipidemia, hyperinsulinemia, and glucose homeostasis are common in these patients, making the IGF system a biomarker of human CRC susceptibility and prognosis." (PMID 34422629, 2021). "Moreover, mother’s obesity before pregnancy may influence IGF2 methylation and gene expression." (PMID 23840686, 2013). "The lack of differences in the gene expression of placental ADAM17, PLAU, and IGF2 between the three groups suggests that these genes would not be affected by obesity." (PMID 37408866, 2023).
Obesity (continued). "Taken together, IGF2 depletiondownregulated expression levels of PGC1α and SIRT1, increased ROS production andmitochondrial fission, and decreased mitochondrial biogenesis and ATP production, whichcontributed to the development of fatty liver and obesity." (PMID 33988719, 2021). "Some authors suggest that an initial reduction in serum IGF2 levels may indicate a bad prognosis for weight gain, whereas longer HFD exposition leads to an increase in the circulating IGF2 as in obesity." (PMID 33202914, 2020). "In the adult brain, IGF2 promotes memory consolidation, neurogenesis and cognitive function and it could be involved in structural changes induced by HFD and/or obesity, although this remains to be determined." (PMID 33202914, 2020). "In this regard, we selected four maternally imprinted genes (MEST/PEG1, SNRPN/PEG4, NNAT/PEG5, and SGCE/PEG10), three paternally imprinted loci (H19-IG DMR, IGF2 DMR0, and MEG3-IG DMR) and one obesity related gene HIF3A to check the correlation of male BMI with sperm DNA methylation." (PMID 31246962, 2019). "Taken together, our findings suggest that the down-regulation of Igf2 and Peg3 imprinted genes in adipocytes may be involved in the paternal transmission of HFD-induced obesity." (PMID 24416415, 2014). "Therefore, the down-regulation of Peg3 and Igf2 and up-regulation of Igf2r in adipocytes from HFD-induced obesity mice is specific to B6 mice." (PMID 24416415, 2014). "The cross-product term for obesity and IGF2 DMR methylation, however, was not statistically significant (p = 0.78)." (PMID 22392079, 2012). "Insulin and IGF2 (11p15.5) are candidate genes for complex traits, including type I diabetes mellitus (T1DM), type II diabetes mellitus (T2DM) and obesity with onset especially in childhood and middle-age." (PMID 21637566, 2010). "The DNA methylation at the insulin like growth factor 2 (IGF2)/H19 gene locus, that may be induced by intrauterine hyperglycaemia, and is a cornerstone that links birth weight and foetal metabolic programming of late onset obesity." (PMID 29050364, 2017). "In addition, hypomethylation of IGF2 DMR was also associated with elevated plasma IGF2 protein concentrations and higher birth weight in infant born to obesity women while patterns of association were not apparent at the H19 DMR." (PMID 25269528, 2014). "In both sexes, circulating levels of free IGF1, total IGF1, IGF2 and IGFBP3 are reported to be increased in humans and rodents with obesity, although some studies found no changes in total IGF1 in patients with obesity." (PMID 33202914, 2020). "Diet-induced obesity affects expression in many tissues, but we first focused on expression in WAT because expression of an imprinted gene, Igf2, was significantly affected in WAT and was not significantly affected in other tissues [8, unpublished results]." (PMID 26868178, 2016). "Interestingly, Igf2 and Peg3, which are paternally expressed imprinted genes involved in the regulation of body fat accumulation, were down-regulated in B6 and (PWK×B6) F1 mice, which are susceptible to HFD-induced obesity, but not in PWK and (B6×PWK) F1 mice, which are resistant." (PMID 24416415, 2014). "As seen here, IGF2 mRNA levels in VAT were previously reported to be reduced in C57 mice in response to HFD-induced obesity; however in PWK mice, which are resistant to HFD-induced obesity, they are not." (PMID 33202914, 2020).